CD4 (CD4 molecule)
Diseases named in the same sentence as CD4 in open-access papers (continued):
Sharing a sentence is not in itself a finding about the gene and the disease.
cancer (continued). "Studies have reported that repressed CD4, CD8 and T cell and activated B cells infiltration indicated an immune suppression microenvironment in cancer." (PMID 36998462, 2023). "First, we collected the single-cell RNA-sequencing pan-cancer atlas of T cells and analyzed the expression of CD226 in CD4+T cells, CD8+T cells, and Tregs." (PMID 37056782, 2023). "The anti-cancer response following APC-T cell interaction involves the APC-secreted IL-1, which activates IL1R1 signaling in CD4+ T cells and promotes production of many effector cytokines." (PMID 37563620, 2023). "Further analyzing transcriptomic data exhibited significantly positive Pearson correlation coefficients for most cancer entities between CXCR4 and the T cell co-receptors CD4 and CD8A, as well as IRF1 and CTLA4." (PMID 36672341, 2023). "With the increase of CD4+ and CD8+ specific T cells, studies on HCC and other cancers have found that ablation will lead to the reduction of immunosuppressive regulatory T cells (Treg)." (PMID 36761748, 2023). "While some reports described a reduction of CD8 TILs in cancer milieu after NAC, others showed an increase on TILs count or an inversion on the CD4/CD8 ratio." (PMID 36830775, 2023). "For the majority of cancer types, there was a significant correlation between CLCN4 expression and immune cell infiltration, especially CD4+ T cells." (PMID 37671947, 2023). "More importantly, the average CD4+ and CD8+ T cell populations in small-size cancer vaccines (dLLC-MS) are higher those in in large-size cancer vaccines (dLLC-ML)." (PMID 38259474, 2023). "In EC, the accumulation of CD4+CD25+‐ and Foxp3+‐Tregs was supposed to be connect with cancer cell proliferation and poor clinical prognosis." (PMID 36226375, 2023). "Therapeutic cancer vaccinations for HPV-related cancers have focused especially on long HPV peptides, which can elicit an increase in the number and activity of HPV-16-specific CD4 and CD8 T cells." (PMID 36175673, 2023). "Studies in recent years have shown that immune cell infiltration, such as CD4+T cells, CD8+ T cells, MDSC, CAF, etc., plays a crucial role in cancer immunotherapy." (PMID 37301547, 2023). "In almost all cancers detected, T cell CD4+ Th2 and common lymphoid progenitor were positively correlated with PHF5A expression, while T cell CD4+ central memory was negatively correlated with it." (PMID 37845358, 2023). "The percentage of T cells CD8, T cells CD4 memory active, T cells CD4 memory resting, Macrophages M1, B cells naive were relevant to the PRLPM riskcores of most cancer types." (PMID 36917093, 2023). "For cancer patients, cell counts of CD3+ T, CD3+CD4+ Th, CD3+CD8+ CTL, CD19+ B decreased with advancing age and stage." (PMID 38102684, 2023). "IDO-reacting CD4+ T cells also respond specifically to DCs pulsed with IDO+ tumor lysates, emphasizing the cancer relevance of IDO-specific T cells." (PMID 36175673, 2023). "Cancer patients showed obviously decreased CD3+ T, CD3+CD4+ Th, CD3+CD8+ CTL, CD19+ B, CD16+CD56+ NK cell counts and lower percentage of PD-1 (programmed cell death protein-1, PD-1) positive cells than healthy control (P < 0.0001)." (PMID 38102684, 2023). "In contrast, in a separate clinical study, PV001-DV induced high activation of cell populations of CD4 and CD8 T cells, NK and NK-T cells, alongside other known anti-cancer effector cells such as γδ T cells." (PMID 37468934, 2023). "NUDCD1 was associated with expression levels of recognized immune checkpoints (anti-CTLA-4) and immune infiltrates (e.g., CD4+ and CD8+ T cells) in some cancers." (PMID 37338527, 2023). "The prognostic value of CD4+FOXP3+ T cells has been confirmed in many cancers, but contradictory results have also been found in some cancers." (PMID 37868998, 2023).
cancer (continued). "Together, these data suggest that targeting the PD-1/PD-L1 axis with PIK-93 and anti–PD-L1 antibodies further increases the recruitment of not only CD4+/CD8+ TILs but also M1 macrophages, thus enhancing the antitumor immune response to cancer immunotherapy." (PMID 37027467, 2023). "The BHMDI nano-composites enhanced dendritic cell maturation, leading to the increase in CD4+ and CD8+ T cells, and simultaneously decreased the fraction of alternatively M2-type TAMs in malignancies." (PMID 36903458, 2023). "Most importantly, our data showed that the BNT162b2 vaccine induced a significantly higher CD4+ and CD8+ T-cell (Ag2) response after the second vaccination compared to the BBIBP-CorV vaccine in cancer patients." (PMID 37515127, 2023). "Cell counts of CD3+ T, CD3+CD4+ Th, CD3+CD8+ CTL, CD16+CD56+ NK, CD19+ B and the percentage of PD-1 positive cells decreased in cancer patients, supported impaired innate and adaptive immunity and lower T cell activation." (PMID 38102684, 2023). "Use of or codelivery of adjuvants that promote alternative CD4+ T cell fates such as Tfh and germinal center formation, with GLA-SE or A-910823, could enhance formation of tertiary lymphoid structures, which are highly associated with improved therapeutic benefit of cancer vaccines." (PMID 38063199, 2023). "In a wide range of cancer, our investigation found that PTGES3 expression has substantial relationships with the infiltration degree of CD4+ T cells and MDSCs." (PMID 37274225, 2023). "The correlation between SLC25A1 expression and CD4 + T cells, CD8 + T cells, neutrophils, myeloid dendritic cells, macrophage, and B cells was systematically evaluated at the pan-cancer level in this study." (PMID 37981593, 2023). "Injection of irradiated cancer cells stimulated to secrete GM-CSF led to tumor antigen presentation by dendritic cells (DC), activation of CD4 + and CD8 + T-cells (TC) and killing of cancer cells." (PMID 36376606, 2023). "CF33-hNIS-antiPDL1 treatment produced functional anti-PD-L1 scFv, which blocked surface PD-L1 binding of live cancer cells and increased CD8+CD107α+ and CD4+CD107α+ T cell percentages while decreasing EGF, PDGF, soluble anti-PD-L1, and IL-10." (PMID 37762490, 2023). "A pan-cancer analysis showed that ENO-1 expression correlated with immune cell infiltration, including B cells, CD8+ and CD4+ T-cells, macrophages, neutrophils, and dendritic cells." (PMID 36768924, 2023). "Taken together, LAIT has great potential to prolong cancer patient survival by activating CD8+, CD4+ T cells as well as B cells." (PMID 38550850, 2023). "Not only the cells mentioned here, but also lots of other immune cells, such as dendric cells, CD4+/CD8+ cells and Treg cells, are acting sites in anti-cancer immunotherapy that surely promise therapeutic treatments for curing cancer." (PMID 38067344, 2023). "It has been shown that the peripheral blood numbers of CD4+, CD8 + T lymphocytes, and T-regs are important indicators for the activity of the immune system against cancer." (PMID 37704828, 2023). "Compared to EGFR mutants, EGFR wild-type carcinomas had higher numbers of CD8+ T cells, CD4 memory activated T cells and neutrophils, and lower numbers of resting dendritic cells and resting mast cells, in two of the datasets." (PMID 37033978, 2023). "exogenously treated both CD4+ and CD8+ T cells, isolated from cancer specimens and found that MDA-7 in a dose-dependent manner enhanced cytolytic activity of CD8+ T cells (as monitored by target cell death and IFN-γ expression)." (PMID 35402258, 2022). "Strong positive correlation was observed between expression of two hub genes and infiltrating levels of CD4+ T cells, while weak negative correlation could be found between expression of two hub genes and infiltrating levels of cancer associated fibroblast or endothelial cells." (PMID 35903365, 2022).
cancer (continued). "The best outcomes typically occur at the highest CAR T-cell doses, at a 25:75 CD4+:CD8+ ratio, at moderate to strong CAR affinity, and with high cancer cell antigen density." (PMID 35903149, 2022). "We decided to focus exclusively on CD4+ Tregs, because too little had been published on the role of CD8+ Tregs in cancer for a reliable analysis: we found only three articles on CD8+ Tregs and one on CD4+CD8+ Tregs among the 341 articles we analyzed." (PMID 35740658, 2022). "On the other hand, the immune suppression molecule galectin-9 (Gal9) was primarily expressed on CD4+CD25+ Tregs in OS, with significantly higher frequencies than in non-cancer controls, as well as higher than other solid tumors." (PMID 35433427, 2022). "T lymphocytes are usually the major components of TILs, among which CD4+ T helper cells (e.g., Th1), CD4+CD25+ regulatory T cells (Tregs), CD8+ cytotoxic T cells are frequently observed in various cancers." (PMID 36119047, 2022). "IL-27 is known to directly impact both CD4+ and CD8+ T cells and both cell types have a role in promoting cancer vaccine efficacy." (PMID 35529885, 2022). "Mechanically, intratumoral inoculation of the ΔGRA17 mutant T. gondii strain can activate CD4+ T cells, CD8+ T cells and NK cells and decrease the expression of PD-1 in CD8+ T cells of hosts to improve immunological response to anti-cancer therapy." (PMID 36540800, 2022). "Cytotoxic T-lymphocytes (CTLs), also known as CD8+T cells, and helper T cells, also known as CD4+ T cells (TH1, TH2, and TH17), are the most prominent components of anti-cancer immunity." (PMID 36686754, 2022). "TILs included CD4+, CD8+, and FOXP3+ T cells, and all subsets were significantly reduced in the cancerous tissues compared to the cancer stromal tissues." (PMID 36458816, 2022). "The correlation was evaluated between MCM2 expression and the infiltration of six immune cell types (B cells, CD4+ T cells, CD8+ T cells, dendritic cells, macrophages and neutrophils) and the purity in 32 TCGA cancers and subtypes." (PMID 35693940, 2022). "Helper CD4+ T cells and cytotoxic CD8+ T cells mediate anti-tumor immunity through recognizing and killing cancer cells, but immunosuppressive activities within TME makes CTLs dysfunctional as well as causes T cells exhaustion." (PMID 36686754, 2022). "For cytokines, CCL5 is highly expressed in CD8 + T cells, NK Cells, NKT Cells, CD4 + T Memory Cells, Plasma Cells, and Langerhans Cells and strongly interacts with SDC1 and SDC4 in Cancer Cells, affecting cancer progression, development, and the survival." (PMID 36401283, 2022). "The protein vaccine was constructed using the rigorous immunoinformatics analysis and investigation of several immune system parameters, considering B cell epitopes and CD4 and CD8 induced epitopes as the most important cells to respond to cancer cells." (PMID 35463817, 2022). "(E) The numbers of CD4+, CD8+, and FOXP3+ T cells in cancer tissues of BJCYH cohort were compared between VPS9D1-AS1 negative and positive tissues." (PMID 36458816, 2022). "CD4+CD25+FOXP3+Treg cells play a key role in the aggressiveness of diseases and cancers by regulating the immune response." (PMID 35664563, 2022). "Cytotoxic CD8+ T cells and CD4+ T helper cells play key roles in adaptive immunity with increases in CD8+ and CD4+ promoting cancer immunotherapy." (PMID 37325609, 2022). "The inclusion of CD4 T-cell targeting in vaccination protocols has recently led to superior, integrated CD4 and CD8 T-cell responses in cancer patients." (PMID 35572552, 2022). "In cancer patients CD1c+ cells were shown to represent DCs that are able to stimulate cytotoxic CD8+ and CD4+ helper T cells." (PMID 35955602, 2022). "As we know, patients with cancer always show an immunosuppressive state; given this, we performed FACS to detect the percentage of CD4+T and CD8+T cells as well as the exhaustion of CD8+T cells." (PMID 36479137, 2022).
cancer (continued). "Worse outcomes, in which cancer cells grow beyond their initial plated count, occur at low CAR T-cell doses, at 100:0 and 0:100 CD4+:CD8+ ratios, with the weakest CAR affinity, or with lower cancer cell antigen expression." (PMID 35903149, 2022). "In the present study, ASCL2 expression was significantly correlated with the infiltration levels of CD4+ T cells, CD8+ T cells, B cells, neutrophils, and dendritic cells in various cancer types, including COAD." (PMID 35774798, 2022). "The increase in the patient’s CD4 cell count allows the individual’s immune system to recover and produce more CD4 cells which fights off infections and other HIV-related cancers." (PMID 35704636, 2022). "Specifically, we identified that the use of high doses of weak CAR T-cells with intermediate CD4+:CD8+ ratio and a maximized difference between cancer and healthy cell antigen expression produces the most effective treatments." (PMID 35903149, 2022). "CD57 is a marker of terminally differentiated, non-proliferative T cells (senescence and exhaustion) and the frequency of CD57+CD4+ and CD57+CD8+ T cells increases with age as well as with cancer and chronic infections." (PMID 36003367, 2022). "We found that using the proportions of fibroblasts, epithelial cells, TIIC-like macrophages, PBMC-like CD4+T cells, and monocytes from the TIIC + PBMC approach, cancer recurrence was predicted with an AUC of 0.69." (PMID 36345336, 2022). "S-specific CD4 T-cells were detectable in patients with previous SARS-CoV-2 infection, especially in cancer patients." (PMID 36139625, 2022). "Infusion of cell products composed of CD4+ and CD8+ TCR-Ts targeting an MHC class I-restricted HPV-16 E7 epitpope led to objective clinical responses in patients with metastatic HPV-16+ cancers." (PMID 35928827, 2022). "Cytoplasmic PKC-θ is a feature of normal CD4+ and CD8+ T cells in healthy individuals, while mesenchymal cancer cell lines and CTCs isolated from patients resistant to immunotherapy show high nuclear bias of PKC-θ expression." (PMID 35326747, 2022). "The anti-tumoral or pro-tumoral roles of CD4+ and CD8+ T cells typify the complexity of T cell subsets function in cancer." (PMID 36685566, 2022). "Previously, peptide vaccine therapy for cancer has predominantly involved the subcutaneous administration of cancer antigens, e.g., 8–10 amino acids (CD8 epitope) or ~13 amino acids (CD4 epitope)." (PMID 36552770, 2022). "In addition, from the current study, we knew that cancer cells tend to prevent the attack of the immunity system, and activate the immune checkpoint to suppress the immune system attacks, thereby inhibiting the function of immune cells such as CD4, CD8, and APC." (PMID 36454396, 2022). "In human cancers the infiltration of both CD8+ and CD4+ T lymphocytes is a common characteristic of tumors that have a favorable prognosis." (PMID 35874810, 2022). "Methylation was significantly negatively correlated with the transcription level of CD4 and LY96 in almost all the cancer types, contributing partially to the low expression of these genes." (PMID 36497433, 2022). "For example, BCAT1 expression was dramatically and positively related to infiltration levels of neutrophil, dendritic cells, CD4 T cells, and CD8 T cells in some cancers (e.g., HNSCC)." (PMID 34984849, 2022). "LAG-3 on CD4+ cells likely interacts with MHC class II on antigen-presenting cells, while LAG-3 on CD8+ T cells and NK cells likely interacts with L-SECtin on cancer cells." (PMID 35205776, 2022). "As highlighted above, a number of studies reported on the development of active TB disease in cancer patients receiving anti-PD-1 therapy, which enhanced IFN-γ production by Mtb-specific CD4 T cells." (PMID 36456824, 2022). "We also found that TSLP from cancers prepares the metastasis “soil”, such as inducing expression of CCL17 in the lungs to recruit CCR4+ cancer cells and their protector CCR4+FoxP3+ Tregs and Th2-skewed CD4+ T cells." (PMID 36104343, 2022).
cancer (continued). "Derouazi, in 2015, created a unique class of cancer vaccines based on recombinant proteins, by combining recombinant protein with Z12, which provides a variety of CD8+ and CD4+ T-cell epitopes expressed by MHC class I and class II alleles." (PMID 36560420, 2022). "In contrast, CD4+ Th2 T cells, memory CD4+ T cells, monocytes and mast cells were negatively correlated with ALKBH7 gene expression in most cancers." (PMID 35222541, 2022). "CD3 bispecific proteins exert antitumor effects by binding to a cancer-specific antigen at the same time they bind to CD3, a molecule expressed on both CD8+ and CD4+ T cells." (PMID 36212425, 2022). "CXCR6 is expressed at the cell surface of T cells, mainly the CD4 Th1, CD8 Tc1 and NKT cells, and on NK or cancer cells." (PMID 36429101, 2022). "Tregs (CD4+ CD25+ Foxp3+) suppress immune responses to infectious pathogens, cancer, allogeneic organs, and stem cell transplantation." (PMID 35742877, 2022). "Chemotherapeutic drugs enhance T lymphocytes, including CD4, CD3, and NK cells in patients with malignant tumors, which are often in the inactive or inhibited state." (PMID 38094221, 2022). "Cancer and normal breast tissue and peripheral blood samples were collected for evaluation of the expression of PD-1 and CD39 on CD4+ and CD8+T cells by flow cytometry." (PMID 35051220, 2022). "In patients receiving anti-PD-1/PD-L1 for the treatment of HPV-induced malignancies, circulating PD-1+CD39+ memory CD4 T cells were predictive of the response to therapy." (PMID 35954341, 2022). "Like cancer cells, CAP treated CD4+ T cells also displayed significant reductions in ATP-production coupled respiration and coupling efficiency." (PMID 35326381, 2022). "Antitumor cells in the adaptive immune response consist of CD4 + and CD8+ Teff cells, killing cancer cells by different mechanisms." (PMID 36147461, 2022). "By contrast, the FN1-related molecular pairs, including FN1-CD44 (a marker of cancer stem cells) and FN1-(ITGAV + ITGB1), were prompted between SELENOP-Mφ/SPP1-Mφ and FABP4-Mφ/FCN1-Mφ/CD4/CD8 cells in LUAD." (PMID 36008393, 2022). "DCs perform specialized antigen-processing and activate either CD4 + or CD8 + T cells, which mediate the killing of cancer cells and are a positive prognostic factor in multiple solid tumors." (PMID 35022521, 2022). "BRCA, KIRC, and LIHC were the top three cancers with the significant correlation between CD147 and the immune infiltrates in the TME, such as B cell, CD4 and CD8 T cell, dendritic cell, macrophage, and neutrophil (P<0.01)." (PMID 35464411, 2022). "Further, we compared the number of (IE)CD4+ and (IE)CD8+ infiltrates between tumors with different EGFL7-status of cancer epithelium and endothelium." (PMID 35630004, 2022). "Our results identify a population of circulating CD39+ memory conventional CD4 T cells expressing PD-1 and, for the most part, TIGIT and was present at higher proportions in cancer patients than in healthy individuals." (PMID 35954341, 2022). "Preliminary results from clinical trials of cancer vaccines suggest that dendritic cells, peptides, and RNA-based neoantigen vaccines are safe and can induce CD8+ and CD4+ neoantigen-specific T cell responses." (PMID 36528587, 2022). "Despite the fact that cancer-induced exhaustion in CD8+ T cells has been well documented and recognized as a therapeutic target, new research reveals that CD4+ T-cell exhaustion is common in cancer." (PMID 36302799, 2022). "In general, increasing CAR T-cell dose and using higher CD4+:CD8+ ratio treatments results in increased CAR T-cell counts, but it has little effect on cancer and healthy cell killing." (PMID 35903149, 2022). "The regulation of host CD8+/CD4+ T cells and NK cells by coinfected pathogens has also been explored in EBV-driven cancers." (PMID 35281433, 2022). "For iCCA, 5 studies show that CD8+, CD4+ and CD3+ T cells mainly distributed around the cancer itself." (PMID 35392957, 2022).